NLRC5 (NLR family CARD domain containing 5)
Diseases named in the same sentence as NLRC5 in open-access papers (continued):
Sharing a sentence is not in itself a finding about the gene and the disease.
glioma (8 papers, 2019 to 2023). A benign or malignant brain and spinal cord tumor that arises from glial cells (astrocytes, oligodendrocytes, ependymal cells). "Recent studies have found that NLRC5 is also associated with neuronal development and central nervous system (CNS) diseases, such as CNS infection, cerebral ischemia/reperfusion injury, glioma, multiple sclerosis, and epilepsy." (PMID 34220868, 2021). "Another recent study also implicated NLRC5 in promoting the growth of glioma cells by activating the Wnt/β-catenin pathway." (PMID 33671123, 2021). "SCAMP1 also suppresses the malignant proliferation of glioma cells through the miR-499a-5p/LMX1A/NLRC5 axis, highlighting SCAMP1 as an oncogene." (PMID 33493138, 2021). "LMX1A transcriptionally activates the NLRC5 expression, which promotes the malignant biological behaviours of glioma cells through stimulating Wnt/β‐catenin signalling pathway." (PMID 31207033, 2019). "LMX1A and NLRC5 were highly expressed in glioma tissues and cell lines, knockdown of LMX1A or NLRC5 obviously impeded the malignant progression of glioma cells." (PMID 31207033, 2019). "In the further studies, the expression of NLRC5 in glioma cells treated with altering miR‐499a‐5p and LMX1A expression was inspected." (PMID 31207033, 2019). "Our studies revealed that reduction in NLRC5 abundance significantly repressed the activity of Wnt/β‐catenin signalling pathway in glioma cells." (PMID 31207033, 2019). "In conclusion, our study clarifies that SCAMP1/miR‐499a‐5p/LMX1A/NLRC5 axis plays a critical role in modulating malignant progression of glioma cells, which provide a novel therapeutic strategy for glioma treatment." (PMID 31207033, 2019). "In conclusion, the SCAMP1/miR‐499a‐5p/LMX1A/NLRC5 axis serves as a critical regulator of tumourigenesis and progression of glioma, providing a novel therapeutic strategy for glioma treatment." (PMID 31207033, 2019). "Overall, evidence above revealed that miR‐499a‐5p suppressed the expression of NLRC5 by reducing LMX1A in glioma cells." (PMID 31207033, 2019). "Down‐regulation of NLRC5 obviously inhibited malignant biological behaviours of glioma cells through attenuating the activity of Wnt/β‐catenin signalling pathway." (PMID 31207033, 2019). "Our further research showed overexpression of miR‐499a‐5p significantly decreased NLRC5 expression, further inhibited the biological behaviours of glioma cells." (PMID 31207033, 2019). "Therefore, data above clarified that LMX1A knockdown obviously attenuated the activity of Wnt/β‐catenin signalling pathway by down‐regulating NLRC5 expression and restrained malignant behaviours of glioma cells." (PMID 31207033, 2019). "Overall, miR‐499a‐5p could negatively regulate the expression of LMX1A, which directly bound to NLRC5 promoter and modulated its expression, then suppressed the biological behaviours of glioma cells." (PMID 31207033, 2019). "These evidence above suggested that NLRC5 functioned oncogenic role in glioma cells." (PMID 31207033, 2019). "In addition, NLRC5 knockdown remarkably restrained the biological behaviours of glioma cells, which demonstrating that NLRC5 acts as a carcinogen in glioma cells." (PMID 31207033, 2019). "Consequently, data above determined that NLRC5 accelerated malignant progression of glioma cells via enhancing the Wnt/β‐catenin signalling pathway." (PMID 31207033, 2019). "Furthermore, overexpression of LMX1A rescued the tumour‐suppressive impacts of overexpressed miR‐499a‐5p on glioma cells via up‐regulating NLRC5 expression." (PMID 31207033, 2019). "However, whether Wnt/β‐catenin signalling pathway participated in NLRC5‐induced malignant behaviours in glioma cells needs to be explored." (PMID 31207033, 2019).
glioma (continued). "Consequently, the molecular mechanism revealed that knockdown of SCAMP1 increased miR‐499a‐5p expression, which hindered the expression of LMX1A and NLRC5, further led to carcinostatic effects on glioma cells by repressing the activity of Wnt/β‐catenin signalling pathway." (PMID 31207033, 2019). "LMX1A can regulate the expression of NLRC5 (NLR family, CARD domain containing 5) and activate Wnt/β-catenin signaling pathway in glioma." (PMID 35992869, 2022). "This suggests that NLRC5 plays a regulatory role in the development of glioma and is related to IFN signaling and the SCAMP1/miR-499a-5p/LMX1A/NLRC5 pathway." (PMID 34220868, 2021). "However, in recent years, studies have found that NLRC5 is also associated with CNS infection (CNSI), neuronal development, and neuropsychiatric disorders, such as cerebral ischemia/reperfusion (I/R) injury, glioma, multiple sclerosis (MS), epilepsy, schizophrenia (SCZ), and bipolar disorder (BD)." (PMID 34220868, 2021). "In our study, the expression levels of SCAMP1, miR‐499a‐5p, LMX1A and NLRC5 were investigated in glioma tissues and cell lines, meanwhile, the effects on regulating malignant progression of glioma and cross‐talk among SCAMP1, miR‐499a‐5p, LMX1A and NLRC5 were completely clarified." (PMID 31207033, 2019).
hepatocellular carcinoma (7 papers, 2017 to 2024). A malignant tumor that arises from hepatocytes. "Up-regulation of NLRC5 has been shown to contribute to cell proliferation, migration and invasion in hepatocellular carcinoma and clear cell renal cell carcinoma by activating the Wnt/β-catenin signaling pathway in vitro and in vivo." (PMID 38961101, 2024). "Previous studies have shown that NLRC5 promotes the proliferation, migration, and invasion in hepatocellular carcinoma, clear cell renal cell carcinoma, and endometrial cancer." (PMID 38961101, 2024). "For example, NLRC5 is up-regulated in hepatocellular carcinoma and renal carcinoma and contributes to their tumorigenesis." (PMID 38961101, 2024). "Li and colleagues observed elevated expression of NLRC5 protein in human hepatocellular carcinoma (HCC) specimens and in human HCC cell lines HepG2, SMMC-7721 and BEL-7402, and investigated the effects of NLRC5 knockdown and overexpression on cell growth." (PMID 33671123, 2021). "In fact, NLRC5 has been shown to regulate the Wnt/β‐catenin signaling pathway to promote cell proliferation and migration in both clear cell renal carcinoma and hepatocellular carcinoma." (PMID 33428330, 2021). "However, NLRC5 promoted tumor malignancy in hepatocellular carcinoma and clear cell renal cell carcinoma." (PMID 34307322, 2021). "Increased NLRC5 expression has been detected in renal cell carcinoma, hepatocellular carcinoma, gastric cancer, and non-small cell lung cancer (NSCLC)." (PMID 34307322, 2021). "However, the biological function of NLRC5 in hepatocellular carcinoma (HCC) has not been fully demonstrated." (PMID 39132868, 2024).
cervical carcinoma (6 papers, 2017 to 2024). A carcinoma arising from either the exocervical squamous epithelium or the endocervical glandular epithelium. "Other evidence has shown that miR-let-7c-5p inhibits the proliferation and migration of cervical carcinoma cells and negatively regulates NLRC5 protein expression in ethanol-induced hepatic injury." (PMID 34198264, 2021). "On the other hand, miR-34a was reported to be downmodulated by human papilloma virus-16 (HPV-16) in cervical cancer cells, resulting in the upregulation of NLRC5 and consequent attenuation of NF-κB activation and pro-inflammatory cytokine production and virus persistence." (PMID 33671123, 2021).
diabetes (6 papers, 2016 to 2026). "Polymorphisms of BTNLs and sometimes their deficits have been associated with chronic kidney disease, hypertension and diabetes; Nlrc5, a pattern recognition receptor in the MHC I class, regulates NF-κB, type 1 interferon activities and JAK/STAT3 signaling in immune response pathways." (PMID 34204247, 2021). "RNA and whole exon sequencing of tumors from 13 patients who developed ICI-induced diabetes mellitus (ICI-DM) showed significant overexpression of ORM1, PLG, G6PC and a missense mutation in NLRC5." (PMID 37497220, 2023).
endometriosis (6 papers, 2020 to 2025). The growth of functional endometrial tissue in anatomic sites outside the uterine body. "This suggests that NLRC5 overexpression inhibits estrogen receptor β-mediated development and inflammatory responses in endometriosis." (PMID 40508002, 2025). "NLR family CARD domain-containing 5 (NLRC5) acts as a negative regulator in endometriosis by inhibiting inflammation." (PMID 40508002, 2025). "NLRC5 levels are higher in the ectopic and eutopic endometria of endometriosis patients compared to those with leiomyoma, peaking in the ectopic endometrium, and it suppresses IL-6 and TNF-α." (PMID 40508002, 2025). "NLR family pyrin domain containing 3 (NLRP3) and NLR family CARD domain containing 5(NLRC5) have prominent improving effects on endometriosis with altering fibrosis and inflammation in previous studies." (PMID 40034240, 2024). "For example, in endometriosis, the overexpression of NLRC5 promotes the expression of LC3, Beclin1 and the formation of autophagosomes in the lesion, which inhibit disease progression." (PMID 38961101, 2024). "For example, it was reported that there was a negative correlation between NLRC5 expression level and autophagy in endometriosis, suggesting the prognostic potential of the combination of NLRC5 and autophagy in patients with endometriosis." (PMID 38961101, 2024). "Lately, we found the level of NLRC5 was up-regulated in the endometrium with endometriosis compared to the endometrium with leiomyoma, implying the function of NLRC5 in the progression of endometriosis." (PMID 33013364, 2020). "To investigate the role of NLRC5 in inflammation in endometriosis, we first identified the role of TNF-α in NLRC5 in EESCs." (PMID 33013364, 2020). "Western blotting and qRT-PCR were performed to compare the levels of NLRC5 inflammation and autophagy in ESCs of patients with endometriosis and ESCs of patients with leiomyoma." (PMID 33013364, 2020). "In our previous study employing immunohistochemistry, we observe that NLRC5 is up-regulated in ectopic and eutopic endometrium of patients with endometriosis compared to the endometrium of patients with leiomyoma." (PMID 33013364, 2020). "Notably, NLRC5 likely acts as a negative regulator in the development of endometriosis by inhibiting inflammation." (PMID 37033937, 2023). "Nevertheless, the exact molecular mechanism involving NLRC5 and autophagy in endometriosis is unknown." (PMID 33013364, 2020). "We hypothesize that autophagy could be involved in NLRC5-mediated inflammation in endometriosis." (PMID 33013364, 2020). "For example, NLRC5 and P62 were significantly upregulated in the ectopic endometrium, while the elevation of NLRC5 corresponded to autophagy inhibition in endometriosis, which could be used as indicators for the diagnosis of endometriosis." (PMID 32112646, 2020). "However, the mechanism associating NLRC5 and autophagy in endometriosis is still not completely understood." (PMID 33013364, 2020). "Furthermore, the level of NLRC5 in ectopic endometrium is also obviously higher than in the eutopic endometrium, which reaffirms that NLRC5 may have a close relationship the development of endometriosis." (PMID 33013364, 2020). "Collectively, although our previous study suggests that there is a negative correlation between NLRC5 and autophagy in endometriosis." (PMID 33013364, 2020). "Our recent study identify there is a negative correlation between NLRC5 and autophagy in endometriosis, indicating that NLRC5 and autophagy together act as promising predictors in endometriosis patients." (PMID 33013364, 2020).
liver fibrosis (6 papers, 2018 to 2024). "To this end, we induced liver fibrosis by intraperitoneal administration of CCl4 in NLRC5-deficient and control mice for five weeks." (PMID 34712238, 2021). "Sirius red staining of collagen fibers and hydroxyproline content showed comparable levels of liver fibrosis in CCl4-treated NLRC5-deficient and control mice." (PMID 34712238, 2021). "Here, we sought genetic evidence for this hypothesis by evaluating liver fibrosis induced by carbon tetrachloride (CCl4) in NLRC5-deficient mice." (PMID 34712238, 2021). "Negligible changes in Il1b transcript levels and comparable level of liver fibrosis in NLRC5-deficient livers suggest that NLRC5-dependent NLRP3 inflammasome activation plays little pathogenic role in liver fibrosis induced by chemically induced hepatocyte injury." (PMID 34712238, 2021). "To test whether NLRC5 is critical to control liver fibrosis, we treated wildtype and NLRC5-deficient mice with carbon tetrachloride (CCl4) and assessed pathological changes in the liver." (PMID 34712238, 2021). "As NLRC5 knockdown in HSCs was shown to increase NF-κB signaling, we examined whether NLRC5 deficiency promoted liver fibrosis in vivo." (PMID 34712238, 2021). "However, Mmp3 and Timp1 genes, whose impact on liver fibrosis is controversial or unclear, were strongly induced in wildtype mice livers but showed significantly lower or negligible induction in NLRC5-deficient livers." (PMID 34712238, 2021). "We also demonstrated that NLRC5 promoted proliferation and activation of hepatic stellate cells during hepatic fibrosis." (PMID 29692724, 2018). "Next, we compared the extent of liver fibrosis in CCl4-treated Nlrc5-/- and control mice." (PMID 34712238, 2021). "Our findings indicate that even though NLRC5 likely regulates these signaling events in the liver at steady state and after tissue injury, loss of these NLRC5-mediated regulatory mechanisms does not exacerbate liver fibrosis." (PMID 34712238, 2021). "Furthermore, there is increasing evidence that NLRC5 plays a key role in the development and reversal of hepatic fibrosis." (PMID 31824312, 2019). "Taken together, NLRC5 deficiency deregulates hepatic inflammatory response following chemical injury but does not significantly aggravate the fibrogenic response, showing that NLRC5 is not a critical regulator of liver fibrosis pathogenesis." (PMID 34712238, 2021). "Collectively, NLRC5 may take an active part in the occurrence and reversal of hepatic fibrosis." (PMID 31824312, 2019). "Given the prominent role of inflammatory cytokine signaling in liver fibrosis and TNFα-induced NLRC5 expression in the human HSC cell line LX-2, Li and colleagues investigated the role of NLRC5 in modulating the fibrogenic response in HSCs." (PMID 34712238, 2021). "NLRC5 (NLR Family CARD Domain Containing 5) is upregulated in liver tissues of cirrhosis patients, and NLRC5 is increased with carbon tetrachloride and its blockade or knockdown of NLRC5-inhibited liver fibrosis." (PMID 35625564, 2022). "Similarly, the gene coding for the ECM modifying enzyme MMP2 and tissue inhibitor of MMPs-2 (Mmp2, Timp2), which respectively exert anti- and pro-fibrogenic roles in liver fibrosis, were strongly upregulated by CCL4 treatment in both Nlrc5-/- and control mice livers." (PMID 34712238, 2021).
breast carcinoma (5 papers, 2021 to 2025). "It was shown that the miR-4319 was decreased and the NLRC5 was increased in MHC class I – deficient human SKBR3 breast cancer cells after treatment with the plasma." (PMID 40596738, 2025). "Reduced expression of MHC class I and related genes in cancers including breast cancer is frequently associated with genetic and epigenetic reduction of NLRC5 expression." (PMID 40596738, 2025). "Similar to our previous study, it was shown in this study that the expression of NLRC5 in MHC class I – deficient human SKBR3 breast cancer cells was increased after IFN-γ treatment." (PMID 40596738, 2025). "In esophageal squamous cell carcinoma (ESCC) and breast cancer cell lines, elevated NLRC5 expression was associated with lower levels of miR-4319 and miR-125b-5p, which reportedly target NLRC5." (PMID 33671123, 2021). "In terms of promotion of MHC class I expression, the regulatory role of IFN-γ in suppressing miR-4319 and upregulating NLRC5 in MHC-I-deficient breast cancer is considerable and remains unclear." (PMID 40596738, 2025). "Inhibition of miR-4319 by IFN-γ (known as MHC-I increasing agent) to upregulate NLRC5 with upregulation of MHC-I in MHC-I-deficient breast cancer cells, however, remains unclear." (PMID 40596738, 2025). "This study showed that the lncRNA XIST (X-inactivation-specific transcript), upregulated in breast cancer cells, promotes cell proliferation, migration and invasion by increasing NLRC5 expression through sponging off miR-125b-5p." (PMID 33671123, 2021). "Functionally, XIST induced sponging of miR-125b-5p and removed the inhibitory effect of this miRNA on NLRC5, a breast cancer promotor, thus promoting the malignancy of breast cancer cells." (PMID 34527584, 2021). "The relative levels of NLRC5 in SKBR3 breast cancer cells after 24-h treatment with IFN-γ were increased in the groups treated with 50 U/ml and 100 U/ml IFN-γ, with dose dependent tendency compared with the control group with statistical significance (p < .05)." (PMID 40596738, 2025). "The same group recently reported that in MHC-I negative breast cancers the loss of NLRC5 is less frequent than the loss of FHIT, and that FHIT could be used to restore MHC-I expression." (PMID 33671123, 2021). "In LUAD, LUSC and ER+ breast cancer, samples with allelic transcriptional repression had a significantly lower tumor-to-normal ratio of NLRC5 than those without transcriptional repression." (PMID 39358601, 2024). "IFN-γ inhibits miR-4319 and upregulates NLRC5, thereby enhancing expression of MHC-I in SKBR3 breast cancer cells, while limitations include the absence of functional rescue experiments and in vivo validation." (PMID 40596738, 2025).
colorectal cancer (5 papers, 2017 to 2024). A primary or metastatic malignant neoplasm that affects the colon or rectum. "Constitutive activation of interferon signaling pathways has been reported in colorectal cancer (CRC), leading to a strong CD8+ T cell response through stimulation of NLRC5 expression." (PMID 29408916, 2018). "NOD1 and NOD2 expression were enhanced in colorectal cancer, and NLRC5, NLRP6 and NLRP12 had no significant changes compared to the controls." (PMID 34571825, 2021).
atherosclerosis (4 papers, 2024 to 2026). A disease characterized by the build-up of fatty material and calcium deposition in the arterial wall resulting in partial or complete occlusion of the arterial lumen. "Taken together, we uncover a USF1/USP14/NLRC5/Smad2/3 axis that drives atherosclerosis progression via inducing EndMT." (PMID 38424494, 2024). "Collectively, these data demonstrated that activating Smad2/3 pathway was considered the downstream of USP14/NLRC5 axis to contribute to atherosclerosis progression by promoting EndMT in vivo." (PMID 38424494, 2024). "Our findings indicate the contribution of the USF1/USP14/NLRC5 axis to atherosclerosis development via promoting EndMT, which provide effective therapeutic targets." (PMID 38424494, 2024). "In this study, we demonstrated that USF1 transcriptionally activated USP14 to restrain NLRC5 degradation, which prompted atherosclerosis by facilitating EndMT by activation of Smad2/3 pathway." (PMID 38424494, 2024). "Additionally, USF1 transcriptionally activated USP14 to drive atherosclerosis by promoting EndMT through the NLRC5/Smad2/3 axis." (PMID 40413536, 2025).
clear cell renal carcinoma (4 papers, 2021 to 2024). A malignant epithelial neoplasm of the kidney characterized by the presence of lipid-containing clear cells within a vascular network. "NLRC5 has been identified as a regulator of the Wnt/β-catenin signaling pathway in clear cell renal carcinoma, and in the current study we observe increased expression of NLRC5 in FP (log2FoldChange = 3.39, padj = 3.71 × 10−12)." (PMID 33717164, 2021).